IL10 (interleukin 10)
Diseases named in the same sentence as IL10 in open-access papers (continued):
Sharing a sentence is not in itself a finding about the gene and the disease.
COVID-19 (continued). "Moreover, apart from a variety of proinflammatory cytokines (which could possibly play a detrimental role in COVID-19), anti-inflammatory responses including IL-10 and IL-33, which have been implicated in COVID-19 disease severity, were also decreased in vaccinated individuals." (PMID 34348897, 2021). "The only single case of critical COVID-19 among children in our study, had significantly elevated IL-6 (120.31 ng/L), IL-10 (33.38 ng/L), and PCT (0.43 ng/ml), and acute respiratory distress syndrome, acute renal failure and cardiac insufficiency occurred." (PMID 33593415, 2021). "Within COVID-19 patients, only serum IL-6 and IL-10 levels are significantly higher in critical group than in moderate and severe group." (PMID 34064802, 2021). "Two meta-analyses of IL-6 and IL-10 circulating levels found a correlation between the disease severity and mortality in COVID-19 patients." (PMID 34646263, 2021). "Recent findings reported increases in serum inflammatory cytokine (e.g., IL-2R, IL-6, IL-8, IL-10) in severe COVID-19 patients." (PMID 33390771, 2021). "COVID-19 patients have higher serum levels of IL-6, IL-1β, soluble IL-2 R, IL-8, IL-10, IL-17, and TNF-α." (PMID 33757410, 2021). "Those ICU admitted COVID-19 patients exhibited increased plasma levels of IL-2, IL-7, IL-10, granulocyte colony-stimulating factor, monocyte chemoattractant protein- 1, interferon-inducible protein 10, and TNF-α than the non-ICU admitted patients." (PMID 33869282, 2021). "We noticed correlation in the severe COVID-19 group between cytokines IL-6 and IL-10 levels and neutrophils, what was reported by other studies." (PMID 34064802, 2021). "Plasma levels of IL-6, TNFα, IL-1β, IL-10 and IL-21 were significantly higher in Asymptomatic COVID-19 cases as compared with Controls." (PMID 34824360, 2021). "Even more interesting is that IL-10 levels were increased in severe COVID-19 patients, compared to the mild patients." (PMID 34452323, 2021). "However, IL-6, IL-8, IL-10 and IP-10 showed either diagnostic and prognostic classification performance, with an AUC > 0.95 in at least 2 out of the 3 groups (Control vs mild + severe COVID-19; mild vs control + severe COVID-19; severe vs control + mild COVID-19)." (PMID 34675240, 2021). "PIMS-TS children had significantly elevated levels of cytokines, IFNγ, IL-2, TNFα, IL-1α, IFNα, IFNβ, IL-6, IL-17A, GM-CSF, IL-10, IL-33 and IL-Ra in comparison to COVID-19, seropositive and control children." (PMID 33813138, 2021). "Although possible biological relationships exist between the biomarkers (hs-CRP, LDH, serum ferritin, and IL-10) and severity of COVID-19, the effects of these biomarkers in COVID-19 pathogenesis still need validations and further in-depth investigations." (PMID 33410720, 2021). "For example, intensive care unit COVID-19 patients have the highest concentrations of IL-1β, IL-6, and IL-6 to IL-10 ratio." (PMID 34578898, 2021). "Although one line of reasoning can interpret elevated LPS levels in COVID-19 as support for the pro-inflammatory effects of IL-10 (as above), these observations can alternatively also be interpreted as support for IL-10 resistance." (PMID 34234779, 2021). "Cytokine storm was well-described in patients with severe COVID-19, displaying significantly elevated serum levels of IL-6, IL-8, IL-10, IL-2R, and tumor necrosis factor-alpha (TNF-α) compared with those mild and moderate patients." (PMID 35155477, 2021). "Several published works show an increase of IL-10 in critically ill COVID-19 patients despite its general anti-inflammatory nature, even proposing this protein as a prognostic biomarker, together with other well-known inflammatory cytokines such as IL-6." (PMID 35087533, 2021). "The relevance of the innate inflammatory response is effectively supported by the confirmation that IL6 and IL10 are the two cytokines with the highest capacity to predict a fatal course of severe COVID-19." (PMID 34829906, 2021).
COVID-19 (continued). "The pathological role of IL-10 in COVID-19, as well as being a potential therapeutic target, deserves further investigations." (PMID 34938289, 2021). "In the context of COVID-19, frequently, increased levels of IL-10 are reported, usually at later stages." (PMID 34578468, 2021). "The initial evidence is limited, and further studies are warranted to confirm the role IL-10 in COVID-19." (PMID 34646263, 2021). "Regarding Th2 cytokines, COVID-19 patients showed higher levels of IL-6, IL-10 and IL-13, but lower levels of IL-4 (p < 0.001, for all of them)." (PMID 33718270, 2021). "Six features, including disease severity, age, levels of high-sensitivity C-reactive protein (hs-CRP), lactate dehydrogenase (LDH), ferritin, and interleukin-10 (IL-10), were selected as predictors for COVID-19 mortality." (PMID 33410720, 2021). "Many inflammatory biomarkers, such as interleukin (IL)-2, IL-6, IL-10 and tumor necrosis factor, were found higher in COVID-19 patients with severe disease, compared with those with mild or moderate disease." (PMID 34640618, 2021). "COVID-19 patients show elevated IL-10 levels which were known to correlate with disease severity and mortality." (PMID 34177967, 2021). "In critical COVID-19 patients, a rise in serum IL10 levels occurs subsequently to elevated levels of innate inflammatory molecules IL-1β, IL-6, IL-8, and sTNFR1 during the course of the infection." (PMID 34829906, 2021). "The cell source and specific effects of increased IL-10 in patients with severe COVID-19 remain to be defined." (PMID 33232303, 2021). "Cytokine analysis revealed that cytokines IL-6 and IL-10 were elevated in COVID-19 patients on admission and continued to increase significantly as the disease progressed, consistent with previous reports." (PMID 34307393, 2021). "In another study, T cell numbers in COVID-19 patients were negatively correlated with patient survival and with serum IL-6, IL-10, and TNF-α concentrations." (PMID 33445583, 2021). "Although the profile of inflammatory markers is highly variable between patients, a general phenotype of severe COVID-19 is characterized by elevated IL-6, IL-8, IL-10, TNF-alpha, CCL2, CCL3, and CXCL8." (PMID 34830356, 2021). "It has been found that proinflammatory cytokines such as TNF-α, IL-6, IL-10, IL-1β and chemokines increase in COVID-19 patients." (PMID 34284532, 2021). "Some investigations have detected much higher IL-6 and IL-10 levels in patients with critical COVID-19 than in those with severe COVID-19." (PMID 34829906, 2021). "We also assessed plasma levels of three major proinflammatory cytokines, IL-1β, IL-6 and TNFα, and IL-10, an anti-inflammatory cytokine, in COVID-19-naive older adults." (PMID 34868051, 2021). "Critical COVID-19 patients also showed high levels of several proinflammation cytokines, such as IL-2R, IL-8, and IL-6, and anti-inflammatory IL-10, as described by a previous report." (PMID 34712742, 2021). "As another example, monitoring of COVID-19-associated CRS patient cytokine profiles in 2019 revealed higher levels of IL-2, IL-7, IL-10, G-SCF, MCP-1, MIP-1α, and TNF-α in plasma of intensive care unit (ICU) patients versus plasma of non-ICU patients." (PMID 34884813, 2021). "To illustrate the etiological role of IL-10 in COVID-19 we finally propose a viral genotype-endotype-clinical phenotype relationship." (PMID 33746948, 2021). "In contrast, mild COVID-19 patients displayed reduced levels of IL-10 in sera, but the levels of TGF-β were higher than in the sera of healthy donors." (PMID 33692788, 2021). "In this regard, serum IL-10 levels are higher in COVID-19 patients with critical, severe, and moderate symptoms." (PMID 35126355, 2021). "On the one hand, it is thought that elevated serum levels of IL-10 and IL-1RA in COVID-19 patients act as anti-inflammatory or immunosuppressive cytokines to prevent hyperinflammation and are induced by the rapid accumulation of proinflammatory cytokines." (PMID 34858428, 2021).
COVID-19 (continued). "Concerning the results found in the mild COVID-19 subgroups, it was found that mild A group showed higher levels of SIgA, IL-10, and IL-37 than the mild B groups, as well as increased IFN-γ as compared to the negative and others groups." (PMID 33717074, 2021). "Even though IL-6 and IL-10 were noted as predictors for COVID-19 deterioration, all of our patients were followed up in the hospital but not in ICU." (PMID 34384355, 2021). "Here, we present reasons to suspect that IL-10 actively contributes to COVID-19 pathology by impeding resolution of SARS-CoV-2 infection rather than representing a bystander." (PMID 33746948, 2021). "COVID-19 children had elevated levels of IFNγ, IL-2, TNFα, IL-1α, IFNα, IFNβ, IL-6, IL-17A and IL-10 in comparison to seropositive and/or control children." (PMID 33813138, 2021). "During COVID-19, IL-10 production has been identified as a strong predictor of disease severity as IL-10 is elevated in patients with severe disease compared to nonsevere disease." (PMID 34473802, 2021). "When a machine learning-based model was applied, CRP, age, LDH, ferritin and IL-10 turned out to be predictors of COVID-19 related mortality." (PMID 34539644, 2021). "In conclusion, both active AOSD and severe COVID-19 patients showed elevated Gal-3, Gal-9, and cytokines, including IL-1β, IL-1Ra, IL-10, IL-6, IL-18, and TNF-a, supporting a common link of cytokine storm in the pathogenesis of both diseases." (PMID 34367188, 2021). "A recent perspective proposed treating COVID-19 with B-1a cells to mitigate the cytokine storm and eliminate viral loads by B-1a cell-produced IL-10 and natural IgM, respectively." (PMID 33708213, 2021). "Recent published studies have reported that elevated inflammatory cytokine (such as TNFα, IL-1β, IL-6, IL-10, IL-17, IL-18, and IFNγ) levels were seen in active COVID-19 cases compared to healthy donors." (PMID 34348897, 2021). "SARS differs from COVID-19 in that IL-10 is only increased in convalescent SARS-CoV patients and but not with other SARS disease phenotypes." (PMID 34454610, 2021). "The cytokine profiling of COVID-19 patients in our study provided further evidence that the CRS-associated cytokines, such as IL-6, IL-1β, IL-10, IL-18, and IFN-γ, were dramatically elevated in severe patients." (PMID 33712622, 2021). "Severe COVID-19 cases had elevated the levels of various cytokines, including granulocyte colony stimulating factor, IL-10, TNF-α, MIP-1α and MCP-1." (PMID 34064802, 2021). "A high level of IL-10 has also been reported; however, the level of IL-10 was lower in patients with severe COVID-19 when compared to patients with mild COVID-19." (PMID 33557908, 2021). "Here, we found increased IL-10 levels in the mild A COVID-19 subgroup as compared to the mild B COVID-19 subgroup." (PMID 33717074, 2021). "Elevated concentration of IL-6 had been indicated as a stable indicator for the progression and adverse endpoint of COVID-19, and IL-6 and IL-10 were significantly related with the positivity duration of SARS-CoV-2, which were consistent with our findings." (PMID 33542929, 2021). "It was recently shown that the total number of CD4+ T cells, CD8+ T cells, B cells, and NK cells in patients was markedly decreased in the most severe forms of COVID-19 and that there is an increase of IL-2, IL-6, IL-10, and IFN-γ." (PMID 34552938, 2021). "Although some COVID-19 patients showed a high release of IL-10 in the supernatant of T-cell-activated whole blood, the difference between healthy controls and patients was not significant." (PMID 34021143, 2021). "It has been revealed that patients with severe COVID-19 present higher levels of IL-2, IL-6, IL-7, IL-10, and TNF-α than the patients with mild and moderate disease." (PMID 34088317, 2021). "Although COVID-19 patients have decreased CD4+ and CD8+ T cells, increased IL-6 and IL-10 levels, associated with cytokine storm, are linked to disease severity." (PMID 34244584, 2021).
COVID-19 (continued). "Elevated levels of inflammation-related cytokines, including IL-6, IL-8, and IL-10 were found in patients with COVID-19." (PMID 34031269, 2021). "Another mechanism that can suppress NK cell antiviral activity is the elevated IL-6 and IL-10 levels in COVID-19 through the down-modulation of the activating receptor NKG2D." (PMID 35062250, 2021). "In a meta-analysis, serum levels of interleukin-2 (IL-2), IL-2R, IL-4, IL-6, IL-8, IL-10, tumor necrosis factor-alpha (TNF-α), and interferon-gamma (INF-γ) were found to be associated with severe COVID-19 cases." (PMID 34855834, 2021). "Previously, we found that individuals with severe COVID-19 have high systemic levels of IL-6, IL-10, VEGF and sCD40L." (PMID 35082777, 2021). "Assess Efficacy of HB-adMSCs to treat COVID-19 patients.Primary endpoints: detect change from baseline in inflammatory markers (IL-6, IL-10, TNF-alpha, C Reactive protein), improving oxygenation, and decreasing time to return to room air (RTRA)." (PMID 33815867, 2021). "Univariate analyses were carried out, and 6 cytokines including G-CSF, HGF, IL-10, IL-18, M-CSF and SCGF-β were found to be associated with the severity of COVID-19." (PMID 34489933, 2021). "IL-10/IL-6 is an index of the anti-inflammatory/pro-inflammatory balance which is severely disturbed in severe COVID-19, much more than in bacterial sepsis." (PMID 33682678, 2021). "Consistent with prior reports, levels of IL-10 are significantly higher in patients with MIS-C than in those with Severe COVID-19 13,21." (PMID 34893640, 2021). "Of the two plasma and nasopharyngeal cytokines differentially expressed between healthy donors and patients with COVID-19 (IL-10 and CCL2), both were increased during infection in plasma and nasopharyngeal samples." (PMID 34471264, 2021). "In a meta-analysis of 6320 COVID-19 patients, elevated WBC count, neutrophil count, prothrombin time, D-dimer, fibrinogen, ESR, procalcitonin, IL-6, and IL-10 were all found to be associated with severe disease, ICU admission, and poor outcome in COVID-19." (PMID 34584599, 2021). "Then, we highlight patient studies on COVID-19 that identified increased blood levels of the major anti-inflammatory cytokine interleukin 10 (IL-10) that display a dynamic pattern different from other cytokines and not seen in SARS." (PMID 33746948, 2021). "In light of preliminary data, IL-10 displayed higher levels in patients with sepsis and serious COVID-19." (PMID 34059076, 2021). "In severe COVID-19 infected individuals, interleukin (IL)-6, IL-10, and TNF-α are significantly higher, and it is known that proinflammatory cytokines and chemokines contribute to the occurrence of ARDS." (PMID 33467466, 2021). "A study that enrolled 548 patients found that high cytokine levels (IL-2R, IL-6, IL-10, and TNF-α) were significantly associated with severe COVID-19 on admission, whose findings correspond with our results." (PMID 34489933, 2021). "Although IL-10 is considered an anti-inflammatory cytokine, its paradoxical behaviour was observed in COVID-19 and several other conditions." (PMID 33679215, 2021). "In an early study of 548 COVID-19 inpatients in China, men had higher levels of hsCRP, ferritin, and IL-10, but lower lymphocyte count compared with women even after adjustment for age and comorbidities." (PMID 33909684, 2021). "TNF-α and IL-10 directly correlate with COVID-19 severity and are synonymous with patient deterioration." (PMID 34368648, 2021). "Second, a score for the Severe COVID-19 patients was defined as S2 = (IL-6+sCD40L/1000 + VEGF/10 + 10*IL-10)/(IL-2 + IL-8)." (PMID 34262570, 2021). "Looking at longitudinal changes of cytokine levels between the two treatment groups, we found that patients on HDx showed an increase in IL-8 and IL-10 levels one week after the COVID-19 diagnosis." (PMID 33808205, 2021). "dOne prior meta-analysis has recommended serum ferritin and IL-10 as candidate biomarkers for predicting COVID-19 progression to critical illness." (PMID 33410720, 2021).
COVID-19 (continued). "Induction of the anti-inflammatory cytokine IL-10 was also increased, similar to what is observed in COVID-19 patients." (PMID 33979301, 2021). "The cytokine profile of HLH is characterized by high levels of IFN-γ, TNF-α, IL-6, IL-10, and IL-12, a similar pattern to what is found in severe COVID-19." (PMID 33557908, 2021). "In COVID-19 patients, the pro-inflammatory cytokines like IL-1, IL-2, IL-6, IL-7, IL-10, IP-10, and TNFα as well as chemokines like IL-8 are found in higher concentrations." (PMID 33981235, 2021). "In this Brief Research Report, we show our preliminary data on a possible role for IL-10 in trying to mitigate COVID-19 pathogenesis, by enhancing ACE2 expression in lung cells (see Graphical Abstract)." (PMID 34646263, 2021). "In both moderate and severe COVID-19 patients, the average concentrations of IL-4, IL-6, IL-10, CCL2, IFN-γ, and TNF-α (P<0.05) were higher than those in healthy donors." (PMID 34489974, 2021). "In the following, we consider cellular sources of IL-10 and the evidence for IL-10 producing cells in COVID-19 patients." (PMID 33746948, 2021). "Evidence has suggested that cytokine storms such as higher concentrations of IL-6, IL-8 and interleukin-10 (IL-10) were related to the prognosis of COVID-19 patients." (PMID 33638944, 2021). "In COVID-19 patients, the anti-inflammatory response mediated by molecules such as IL-10, IL-4 and TGF-β is finalized to balance the initial proinflammatory response described in several models." (PMID 34441796, 2021). "The cellular source of increased IL-10 in blood of COVID-19 patients as well as IL-10 protein levels in the SARS-CoV-2 infected lung have not been reported so far." (PMID 33746948, 2021). "Considering only the COVID-19 positive patients, we found that those with higher concentrations of IL-10 (>200 ng/L) or IL-6 (>100 ng/L) had higher concentrations of CCL2, galectin-3, and PON1 concentrations." (PMID 34205807, 2021). "In COVID‐19, the increased amounts of cytokines (e.g. IL‐1β, IFN‐γ, IP‐10, IL‐10 and IL‐4) is associated with COVID-19 severity." (PMID 34118952, 2021). "In vitro studies showed that MAIT cell IFN-γ and granzyme B production were impaired by coculture with CD14+ cells from patients with severe COVID-19 and this is mediated by monocyte-derived IL-10 and IFN-α." (PMID 35381137, 2021). "Yet, in the absence of direct evidence for this pro-inflammatory process in COVID-19, we here consider the established anti-inflammatory effects of IL-10 as critical for its proposed role in both lung protection and interference with viral clearance." (PMID 33746948, 2021). "The drastic early rise in IL-10 in severe cases of COVID-19 is a distinguishing and seemingly paradoxical observation in light of IL-10’s classical role as an anti-inflammatory cytokine." (PMID 34234779, 2021). "The analysis of basal cytokine profile revealed that COVID-19 patients had higher levels of IL-10 (15.2 (12.5) vs. 1.2 (1.4) pg/mL, p = 0.02), while the levels of IL-6, IL-8 and sTLR4 were comparable." (PMID 33808205, 2021). "used the databases to compare cytokine profiles between AOSD and COVID-19, and revealed higher IL-6 and IL-10 in severe COVID-19 than in AOSD." (PMID 34367188, 2021). "Severely ill patients hospitalised with COVID-19 exhibit increased levels of Interleukin (IL)-1β, IL-2, IL-6, IL-7, IL-8, IL-10, IL-17, granulocyte colony stimulating factor (G-CSF), monocyte chemoattractant protein 1 (MCP-1) and tumor necrosis factor (TNF)." (PMID 34205262, 2021). "Two meta-analyses on IL-6 and IL-10 circulating levels found a correlation between the disease severity and mortality in COVID-19 patients." (PMID 34646263, 2021). "Involved cytokines seem to be different, with a more oriented IL-6, TNF, interferon and CXCL5 profile in COVID-19 and a more defined role for IL-6 and IL-10 in influenza." (PMID 34524562, 2021).